YAF2 (YY1 associated factor 2)
Description:
Binds to MYC and inhibits MYC-mediated transactivation. Also binds to MYCN and enhances MYCN-dependent transcriptional activation. Increases calpain 2-mediated proteolysis of YY1 in vitro. Component of the E2F6.com-1 complex, a repressive complex that methylates 'Lys-9' of histone H3, suggesting that it is involved in chromatin-remodeling.
Tractability: PROTAC: ubiquitination databases record sites on it.
Gene: Protein-coding gene on chromosome 12 (42,157,104 to 42,238,349, reverse strand). Ensembl gene ENSG00000015153.
Subcellular location: Nucleus
Subcellular location (Human Protein Atlas): Nucleoplasm
Pathways (Reactome):
Gene expression (Transcription): RUNX1 interacts with co-factors whose precise effect on RUNX1 targets is not known; Transcriptional Regulation by E2F6
Gene Ontology:
Molecular function: protein binding; transcription coactivator activity; transcription corepressor activity; DNA binding; transcription coregulator activity
Biological process: negative regulation of DNA-templated transcription; positive regulation of DNA-templated transcription; heterochromatin formation; regulation of DNA-templated transcription
Cellular component: nucleoplasm; nucleus; chromatin; PRC1 complex
Genetic constraint (gnomAD): Loss-of-function variants: 7 observed, 13.77 expected, observed/expected ratio (o/e) 0.51, 90% interval 0.29 to 0.95. The upper end of that interval is the gene's LOEUF score, 0.95, which puts it in group 4 of 6, group 1 being the genes least tolerant of losing a copy. Missense variants: 133 observed, 179.61 expected, observed/expected ratio (o/e) 0.74, 90% interval 0.64 to 0.86. Synonymous variants: 67 observed, 64.61 expected, observed/expected ratio (o/e) 1.04, 90% interval 0.85 to 1.27.
Homologues: Orthologues: chimpanzee YAF2 (100% identical), dog YAF2 (100% identical), pig YAF2 (99% identical), guinea pig YAF2 (94% identical), rat Yaf2 (92% identical), mouse Yaf2 (91% identical), rabbit YAF2 (89% identical), zebrafish yaf2 (83% identical), Drosophila melanogaster RYBP (42% identical), Caenorhabditis elegans tag-294 (34% identical). Paralogues in human: RYBP (64% identical).
Diseases named in the same sentence as YAF2 in open-access papers:
YAF2 is named in the same sentence as 8 diseases in open-access papers, as found by Europe PMC text mining. Sharing a sentence is not in itself a finding about the gene and the disease. The quoted sentences say what the papers report.
breast carcinoma (1 paper, 2021). "For example, circRGPD6 inhibits cancer stem cell-regulated metastasis of breast cancer by the miR-26b/YAF2 signaling." (PMID 34789263, 2021).
leiomyosarcoma (1 paper, 2023). An uncommon, aggressive malignant smooth muscle neoplasm, usually occurring in post-menopausal women. "In the leiomyosarcoma sample, the genes involved in cell growth, survival, and proliferation (MFHAS1, YAF2, SOX5, and PAK5) were also overexpressed." (PMID 36673024, 2023).
non-small cell lung carcinoma (1 paper, 2023). A group of at least three distinct histological types of lung cancer, including non-small cell squamous cell carcinoma, adenocarcinoma, and large cell carcinoma. "High expression of YAF2 has been found in non-small cell lung cancer cells (NSCLCs), where it allows cell invasion and migration, preventing apoptosis." (PMID 36673024, 2023).
cancer (4 papers, 2012 to 2023). A tumor composed of atypical neoplastic, often pleomorphic cells that invade other tissues. "Interestingly, in agreement with PRC1 purifications from cancer cell lines, the PCGF1-containing complex associates with RYBP or YAF2 but fails to integrate chromobox domain-containing (CBX) proteins that recognize H3K27me3." (PMID 23256043, 2012).
tumour (1 paper, 2023). "CTS, a water-soluble component of Salvia miltiorrhiza with anti-inflammatory and anti-tumour effects, can downregulate the expression of miR-574-5p by regulating its methylation, thus improving Yaf2 expression and affecting chondrocyte apoptosis." (PMID 37508486, 2023).
YAF2 also shares sentences with these, for which no sentence is quoted: intimal sarcoma (1 paper); osteosarcoma (1); Parkinson disease (1).